LSP1 (lymphocyte specific protein 1)
Diseases named in the same sentence as LSP1 in open-access papers (continued):
Sharing a sentence is not in itself a finding about the gene and the disease.
melanoma (7 papers, 2007 to 2025). A malignant, usually aggressive tumor composed of atypical, neoplastic melanocytes. "Collectively, these results show that specific overexpression of Lsp1 in T cells enhances B16 melanoma growth, which is associated with a decrease in the number and frequency of TILs, particularly CD8+ T cells." (PMID 33020243, 2020). "We demonstrated first that Lsp1 deficiency reduces the growth of B16 melanoma and enhances the infiltration of immune cells into tumor sites in mice." (PMID 33020243, 2020). "Lsp1-deficient T cells more strongly repressed tumor progression in Rag1 KO mice challenged with B16 melanoma as compared with Lsp1-overexpressing T cells and vehicle alone (without mature T cells), which confirms that loss of Lsp1 in T cells specifically mediates the antitumor effect." (PMID 33020243, 2020). "In Lsp1 KO mice treated with anti-PD-1 Ab, the contribution of anti-PD-1 Ab treatment and Lsp1 deficiency to tumor suppression was 59.6% and 40.4%, respectively, as estimated by the degree of decrease in mean tumor volume 14 days after the melanoma inoculation." (PMID 33020243, 2020). "As mentioned in the earlier part of the paper, opposite observations were reported in studies of different cancers, such as in a mouse model of B16 melanoma, LSP1 knockout improved T-cell infiltration and cytotoxicity." (PMID 40038352, 2025). "In a study of melanoma, LSP1 in T cells was reported to promote tumor growth by affecting the migration and infiltration capacity of T cells." (PMID 38879666, 2024). "Previously, it has been shown that the LSP1 knockdown in the murine B16 melanoma leads to infiltration of the tumor with T cells and a decrease in the rate of tumor growth." (PMID 39685635, 2024). "In melanoma, LSP1 decreases the migration and infiltration of T cells toward tumors, thus promoting tumor growth." (PMID 38879666, 2024). "Overall, these results suggest that Lsp1 overexpression in T cells promotes melanoma growth through downregulation of TNF-α+ and IFN-γ+ production by CD8+ T cells, in addition to a marked decrease in infiltrated CD8+ T cells." (PMID 33020243, 2020). "Lsp1 KO mice showed decreased growth of B16 melanoma and increased infiltration of T cells in the tumor mass, which were completely reversed in T cell-specific Lsp1 Tg mice." (PMID 33020243, 2020). "Adoptive transfer of Lsp1 KO or Lsp1 Tg T cells was performed in B16 melanoma-challenged Rag1 KO mice." (PMID 33020243, 2020). "Given that anti-PD-1 therapy has only a modest influence on the number of TILs in melanoma, 42 the growth of melanoma might be additively regressed by the combined effects of 1) increased T cell-mediated cytotoxicity by inhibiting PD-1 and/or LSP1 and 2) enhanced T cell motility by Lsp1 deficiency." (PMID 33020243, 2020). "Collectively, these results show that LSP1 regulates the growth of B16 melanoma in mice, presumably by affecting migration and infiltration of T cells into tumor sites and by modulating the production of antitumor effector cytokines by T cells." (PMID 33020243, 2020). "Adoptive transfer of Lsp1 KO T cells to Rag1 KO mice was more effective in suppressing melanoma growth than transfer of Lsp1 Tg T cells." (PMID 33020243, 2020). "As expected, suppression of melanoma growth was more pronounced in Lsp1 KO mice than in WT mice when treated with PD-1 Ab." (PMID 33020243, 2020). "Adoptive transfer of Lsp1 KO T cells to Rag1 KO mice was more effective in repressing melanoma growth than transfer of Lsp1 Tg T cells." (PMID 33020243, 2020). "In summary, Lsp1 KO mice showed decreased growth of B16 melanoma and increased infiltration of T cells, including CD8+ T cells, in the tumor mass, and these effects were completely reversed in T cell-specific Lsp1 Tg mice." (PMID 33020243, 2020). "We found increased LSP1 expression in tumor-infiltrating T cells that are antigen-experienced in an in vivo melanoma model." (PMID 33020243, 2020).
melanoma (continued). "To determine the immuno-regulatory effects of LSP1 in T cells on tumor progression, we investigated the growth of B16 melanoma in Lsp1 knockout (KO) mice and T cell-specific Lsp1 transgenic (Tg) mice." (PMID 33020243, 2020). "Given that LSP1 in T cells negatively regulates T cell migration, these results suggest that B16 melanoma can evade the antitumor activity of host T cells by upregulating LSP1 expression in T cells within the TME." (PMID 33020243, 2020). "CD8+ T cells infiltrated into B16 melanoma tissue showed similar results, demonstrating that high levels of LSP1 in T cells are possibly induced by B16 melanoma." (PMID 33020243, 2020). "Concurrently, the expression of IFN-γ and TNF-α, major cytotoxic effector cytokines, in CD4+ and CD8+ T cells was higher in B16 melanoma of Lsp1 KO mice than in control mice." (PMID 33020243, 2020). "To address this issue, we subcutaneously inoculated syngeneic B16 melanoma cells into WT and Lsp1 KO mice and then observed tumor growth over 3 weeks." (PMID 33020243, 2020). "Taken together, these observations suggest that genetic ablation of Lsp1 in T cells is a promising strategy to boost the therapeutic efficacy of immune checkpoint inhibitors for melanoma, including anti-PD-1 Ab." (PMID 33020243, 2020). "To further demonstrate the pathological relevance of LSP1 in T cells to tumor conditions, we investigated LSP1 expression levels in TILs of B16 melanoma by flow cytometry." (PMID 33020243, 2020). "The effect was reproduced in an MC38 colon cancer model, indicating that LSP1 regulation of tumor progression is not limited to B16 melanoma." (PMID 33020243, 2020). "LSP1 in T cells regulates the growth of B16 melanoma in mice, possibly by affecting migration and infiltration of T cells into the tumor and by modulating production of antitumor effector cytokines by CD8+ T cells." (PMID 33020243, 2020). "Further, overexpression of Lsp1 in a highly motile melanoma cell line led to formation of hair-like projections." (PMID 22697290, 2012). "Mechanistically, our data suggest how LSP1 regulates B16 melanoma growth." (PMID 33020243, 2020). "Of note, when treated with antiprogrammed cell death protein 1 (PD-1) antibody, inhibition of melanoma growth was more pronounced in Lsp1 KO mice than in Lsp1-sufficient mice, suggesting that Lsp1 depletion additively increases the antitumor effects of anti-PD-1 antibody." (PMID 33020243, 2020). "In sharp contrast with Lsp1 KO mice, Lsp1 Tg mice showed an increase in B16 melanoma growth along with a remarkable decrease in CD8+ T cell infiltration into the tumor sites as compared with WT mice, which indicates that Lsp1-overexpressing T cells directly suppress tumor growth." (PMID 33020243, 2020). "Our data provide the first evidence that LSP1 in T cells regulates the progression of melanoma." (PMID 33020243, 2020). "Notably, Lsp1 KO further potentiates the suppressive effect of anti-PD-1 Ab on melanoma growth." (PMID 33020243, 2020). "Therefore, adoptive cell therapy using LSP1 gene-edited T cells may be an innovative strategy for treating solid tumors, including melanoma." (PMID 33020243, 2020). "Considering that melanoma is resistant to anti-PD-1 therapy, our data provide new evidence that adoptive cell therapy using Lsp1-edited T cells together with anti-PD-1 blockade might be a promising strategy for more effectively treating solid tumors, such as melanoma." (PMID 33020243, 2020). "CD8+ T cells from melanoma tumour mass of LSP1 KO mice exhibited higher migration ability in response to CXCL9 and CXCL10, whereas T cell-specific LSP1 overexpression in transgenic mice resulted in suppressed immune infiltration and promoted melanoma growth." (PMID 40038352, 2025). "Similar to the results obtained in the B16 melanoma model, the growth of MC38 colon cancer cells was significantly diminished in Lsp1 KO mice." (PMID 33020243, 2020).
melanoma (continued). "CD4+ T cells infiltrated into B16 melanoma tissue, but not splenic CD4+ T cells in the same mice, exhibited substantially higher LSP1 expression than splenic T cells of non-tumor-bearing mice." (PMID 33020243, 2020).
ovarian carcinoma (5 papers, 2009 to 2024). A malignant neoplasm originating from the surface ovarian epithelium. "FCGR1A promotes the metastasis of ovarian cancer cells The mechanism by which FCGR1A promotes abdominal metastasis in ovarian cancer patients is related to the regulation of EMT via LSP1." (PMID 38879666, 2024). "Our study is the first to identify FCGR1A as a promoter of metastasis in ovarian cancer through the regulation of LSP1 genes." (PMID 38879666, 2024). "The expression of FCGR1A and LSP1 in ovarian cancer cell lines was examined by quantitative real-time polymerase chain reaction (qRT‒PCR)." (PMID 38879666, 2024).
glioblastoma (4 papers, 2020 to 2025). The most malignant astrocytic tumor (WHO grade IV). "Both RHOG and LSP1 are key regulators of cell proliferation and migration and play a critical role in regulating aggressive cancer cells, such as glioblastoma cells." (PMID 36057587, 2022).
asthma (3 papers, 2022 to 2023). "The study provides new data that deficiency of LSP-1 reduces lung inflammation as well as AHR in a murine model of OVA-induced asthma." (PMID 35733161, 2022). "Our finding of significant reduction in lymphocyte numbers in lungs of LSP1 deficient OVA-challenged mice may be of significance considering there are earlier studies linking the alveolar migration of T-lymphocytes in asthma." (PMID 35733161, 2022). "Taken together, we believe that LSP1 deficiency disrupts recruitment of inflammatory cells and production of cytokines and thereby alleviates physiological and inflammatory outcomes in our murine model of asthma." (PMID 35733161, 2022). "The increase in LSP1 expression on various resident and recruited cells in the asthmatic lungs alludes to a potential for this protein in the pathogenesis of asthma." (PMID 35733161, 2022). "Most of the top eQTM genes have been implicated in lung disease for example PAX8; associated with bronchodilator response in children with asthma, ECHDC3 with obesity and asthma in children, LSP1 with acute lung inflammation, HLA‐DQB1 with asthma and total IgE, and KANSL1 with pulmonary function." (PMID 35344303, 2022). "An OVA-induced mouse asthma model in LSP1-deficient (Lsp1−/−) and wild-type (WT) 129/SvJ mice were used to test the hypothesis that the absence of LSP1 would inhibit airway hyperresponsiveness and lung inflammation." (PMID 35733161, 2022). "We provide new data on the role of LSP-1 in regulation of AHR and lung inflammation in a mouse model of asthma." (PMID 35733161, 2022).
glioma (3 papers, 2020 to 2023). A benign or malignant brain and spinal cord tumor that arises from glial cells (astrocytes, oligodendrocytes, ependymal cells). "In addition, we verified the potential of LSP1 as an independent risk factor for glioma malignancy and a therapeutic molecule for targeted strategies of glioma." (PMID 32003759, 2020). "Taken together, these findings imply the potential of LSP1 as a candidate target in developing novel immune strategies against glioma." (PMID 32003759, 2020). "Second, we explored the value of LSP1 as a prognostic molecule in glioma with data from Chinese Glioma Genome Atlas (CGGA) and The Cancer Genome Atlas (TCGA)." (PMID 32003759, 2020). "This suggested that elevated LSP1 expression was more common in IDH1 wild-type glioma and further reflected different biological genetic background between these two kinds of tumors." (PMID 32003759, 2020). "Due to prominent heterogeneity of molecular nature across different grades of glioma, LSP1 expression was analyzed according to the 2016 WHO grade system." (PMID 32003759, 2020). "Taken together, these data indicate the potential of LSP1 as an independent predicative factor for progressive malignancy in glioma and high LSP1 expression predicts unfavorable survival in glioma." (PMID 32003759, 2020). "We confirmed the potential of LSP1 as a progressive malignancy marker in glioma." (PMID 32003759, 2020). "According to CGGA and TCGA, GBM showed the highest LSP1 expression in comparison to grade II and grade III glioma." (PMID 32003759, 2020). "But LSP1 overexpression in U87 and PGC21 (a primary adherent glioma cell line from a clinical GBM sample) glioma cells didn’t increased their migration abilities." (PMID 32003759, 2020). "Due to the important roles of PD1, LARI1, and OSMR contributing to immunosuppressive microenvironment, we further examined the co-expression of LSP-1 and PD1, LARI1, and OSMR in clinical different grades glioma samples by IHC." (PMID 32003759, 2020). "We further investigated the level of LSP-1 expression in glioma cells (U87, LN229, T98, and PGC21) and non-tumor cells (NHA, THP1(M0), THP1 induced M1 and M2 cells, and PBMC)." (PMID 32003759, 2020). "Lymphocyte specific protein 1 (LSP1) was identified as the only gene in this family which not only has an elevated expression, but also serve as an independent predictive factor for progressive malignancy in glioma." (PMID 32003759, 2020).
hepatocellular carcinoma (3 papers, 2020 to 2025). A malignant tumor that arises from hepatocytes. "Similarly, the LSP1 gene has been reported to inhibit hepatocellular carcinoma growth as a part of its normal function, while LSP1 mutations have been found to increase BC susceptibility in both Caucasian and Han Chinese women." (PMID 33112566, 2020). "In a copy number variation study of human hepatocellular carcinoma tissues, LSP1 is identified as the most frequent gene that manifests deletion and amplifications." (PMID 40038352, 2025). "LSP1 plays a negative regulatory role in cell proliferation and migration of hepatocellular carcinoma, as shown in cell lines and mice." (PMID 40038352, 2025). "Among subjects with hepatocellular carcinoma, LSP1 was downregulated, and those with higher LSP1 expression had a higher 5-year overall and disease-free survival compared with subjects with lower LSP1 expression even after controlling for tumor size, histological grading, and TNM tumor stage." (PMID 36506940, 2022).
Hypertension (3 papers, 2022 to 2025). The presence of chronic increased pressure in the systemic arterial system. "Genome-wide association studies have identified genetic susceptibility loci for hypertension in human lymphocyte-specific protein 1 (LSP1) gene." (PMID 38254711, 2024). "To address the cause of hypertension in LSP1-KO mice, we assessed the expression of eNOS in vascular tissues of the WT control mice and LSP1 null mice." (PMID 38254711, 2024). "The genetic polymorphisms of the CACNA1D, HLAB, CYP11B1, and LSP1 gene regions showed significant association with hypertension." (PMID 36233190, 2022). "Given the profound role of eNOS in pathogenesis of hypertension and the evidence of genetic association between polymorphism in human LSP1 gene and development of hypertension, we hypothesized that deficiency of LSP1 would cause aberrant eNOS expression and activity." (PMID 38254711, 2024). "Together, our data unveil the regulatory role of LSP1 in eNOS expression and activity and provide a novel insight into the molecular mechanism of endothelial dysfunction in hypertension." (PMID 38254711, 2024). "For the hypertension and atrial fibrillation pairing, signals implicating shared causal variants were seen on chromosomes 4, 7, 11, and 17, in the genes FGF5, HOXA13, in the region spanning LSP1 to TNNT3 and that spanning CYTH1 to USP36 respectively." (PMID 40538118, 2025). "Since endothelial dysfunction in hypertension is associated with low NO bioavailability, upregulation of eNOS expression in LSP1 KO mice is potentially mediated by loss of normal negative feedback of NO on eNOS expression." (PMID 38254711, 2024). "Furthermore, eNOS upregulation in LSP1 KO mice could be a compensatory mechanism against high blood pressure in LSP1 KO mice that appears to restore NO bioavailability and to ameliorate for increased cleavage/dissociation of eNOS in vivo in LSP1 KO mice." (PMID 38254711, 2024).
lung carcinoma (3 papers, 2008 to 2014). "This LSP1 region is conserved in mice, and studies have found loss of heterozygosity in this region in breast and lung cancers." (PMID 24681604, 2014).
psoriasis (3 papers, 2017 to 2024). An autoimmune condition characterized by red, well-delineated plaques with silvery scales that are usually on the extensor surfaces and scalp. "We identified GZMB, GNAS, GBP5, FOXP3, LSP1 and CD81 as characteristic genes of psoriasis-associated CD8+ T cells, among which, Granzyme B (GzmB), a serine protease, is produced by natural killer (NK) cells and CD8+ T cells, and is an vital mediator of skin injury, inflammation and repair." (PMID 38915827, 2024). "Only B6 mice, for example, showed significantly decreased expression of Fcer2, Cspg4, Lsp1, and Aldh1b1 with IMQ treatment to recapitulate expression shifts unique to psoriasis lesions." (PMID 28279190, 2017). "Lymphocyte Specific Protein 1 (LSP1) is mainly involved in cytoskeleton construction and cell migration, so we speculated that LSP1 may affect the migration and localization of inflammatory cells such as T cells and indirectly participate in the pathological process of psoriasis." (PMID 38915827, 2024).
rheumatoid arthritis (3 papers, 2022 to 2024). A chronic, systemic autoimmune disorder characterized by inflammation in the synovial membranes and articular surfaces. "Additionally, elevated levels of LSP1 are associated with impaired myosin activity in neutrophils and are also linked to T cell migration in rheumatoid arthritis." (PMID 39444808, 2024). "Increased expression of LSP1 has been implicated in Neutrophil Actin Dysfunction disorder, which is a rare immunologic condition, but LSP1 has also been implicated in T-cell migration in rheumatoid arthritis." (PMID 35733161, 2022). "LSP1 has been shown to regulate T-lymphocyte migration in rheumatoid arthritis." (PMID 35733161, 2022).
Autoimmunity (2 papers, 2022 to 2023). The occurrence of an immune reaction against the organism's own cells or tissues. "Altogether, we found deletion of genes associated with autoimmunity mediated early hematopoiesis (e.g. ZEB2) and influenced the inflammatory potential (e.g. ICAM1, LSP1 and PRKCB) of iPSC-derived myeloid cells, coinciding with the expected phenotype." (PMID 35610203, 2022).
B-cell lymphoma (2 papers, 2007 to 2016). "However, LSP1 expression has been found to increase in NHL class of B-cell lymphoma." (PMID 17207284, 2007). "We then validated that Lsp1 was present in anti-O-GlcNAc immunoprecipitates from the lysates of BCL-1 cells, a murine B-cell lymphoma line." (PMID 27555448, 2016).
Insulin resistance (2 papers, 2013 to 2025). Increased resistance towards insulin, that is, diminished effectiveness of insulin in reducing blood glucose levels. "Upon the intragastric administration in obese insulin-resistant diabetic KKAy mice for 28 days, TLSP, LSP1, and LSP2 all caused a remarkable decrease of fasting blood glucose and significant improvement of insulin resistance and serum lipid metabolism in diabetic mice." (PMID 23762123, 2013). "Consistent with our previous studies, our present study demonstrated that TLSP, LSP1, and LSP2 caused a remarkable decrease of FBG and FINS levels, as well as a significant improvement of glucose tolerance and serum lipid metabolism in insulin resistance obese diabetic KKAy mice." (PMID 23762123, 2013). "Thus, TLSP, LSP1, and LSP2 might improve some of the complications of diabetes caused by insulin resistance." (PMID 23762123, 2013). "In the present study, TLSP, LSP1, and LSP2 significantly elevated the GK activity and decreased G6Pase activity to reduce the procession of gluconeogenesis and increase the contents of hepatic glycogen in the liver, which might be due to amelioration of insulin resistance by the polysaccharides." (PMID 23762123, 2013).